MIF (macrophage migration inhibitory factor)
Diseases named in the same sentence as MIF in open-access papers (continued):
Sharing a sentence is not in itself a finding about the gene and the disease.
viral infections (16 papers, 2010 to 2025). "MIF is also associated with viral infections such as HIV, Influenza, Dengue, Ebola, cytomegalovirus, Japanese encephalitis, and West Nile virus." (PMID 40092999, 2025). "In addition, in certain viral infections such as HIV, MIF can create a microenvironment conducive to viral infection, allowing the virus to evade host defenses and cause persistent infections." (PMID 38275363, 2023). "In addition to bacterial infection, elevated MIF levels are also observed in viral infections, such as those caused by influenza virus, human immunodeficiency virus (HIV), Ebola virus, and dengue virus (DENV)." (PMID 25821355, 2015). "More than 20 of the differentially expressed proteins were directly associated with immunity, apoptosis, tumour development and viral infection and replication, including macrophage migration inhibitory factor (MIF), heat shock protein 90 alpha (Hsp90alpha), and annexin-A1 (Anx-A1)." (PMID 23116199, 2012). "In addition to its potential therapeutic applications, MIF could also play a role in the diagnostic and prognostic aspects of the treatment of viral diseases." (PMID 38275363, 2023). "The either protective or immunopathogenic role of MIF has been described in several bacterial and viral infections." (PMID 28646884, 2017). "The results point to the signaling route involving TLR3, MIF, and TNFα being active in TBE virus infection and contributing to the risk of an overt neuroinvasive disease." (PMID 28646884, 2017). "Hypothesizing the dualistic role of MIF in viral infections, we suggest that the specific effect of MIF may depend on the interplay between MIF and the unique pathogenesis of the virus in question." (PMID 38275363, 2023). "Viral infections and cellular stress result in the secretion of MIF." (PMID 37946732, 2023). "However, further research is needed to fully understand the mechanisms by which MIF influences viral pathogenesis and the potential benefits and risks of targeting MIF in the context of viral infections." (PMID 38275363, 2023). "In addition to its role in the interactions in bacterial infections, MIF plays a key role in the immune system’s response to viral infections." (PMID 38275363, 2023). "In certain viral infections, MIF could have a protective effect by enhancing early immune responses and thus supporting virus clearance." (PMID 38275363, 2023). "This indicates that the nuanced effects of MIF in viral diseases may be shaped by the complex dynamics of host–virus interaction, immune modulation, and the specific organ tropism of the infectious agent." (PMID 38275363, 2023). "During acute injury such as viral infection, type I cells release MIF." (PMID 37853311, 2023). "Based on this, it could be concluded that MIF-targeting drugs have potential therapeutic applications in the treatment of some viral diseases." (PMID 38275363, 2023). "Furthermore, we investigated the relationship between viral infection, MIF, and macrophage infiltration in NPC." (PMID 34407796, 2021). "In addition, viral infection-induced MIF secretion and production seem to be virus- and cell-dependent." (PMID 32545679, 2020). "Furthermore, MIF also contributes to the pathogenesis of various viral infections, including human immunodeficiency virus (HIV), respiratory syncytial virus (RSV), West Nile virus (WNV) and DENV." (PMID 32545679, 2020). "MIF is involved in virus infection, and its target cells are mainly macrophages." (PMID 23116199, 2012). "Inhibitory treatments directed at bystander T cells and the MIF system are possible future immunotherapies, which may be effective for the reduction of disease severity and the protection of infected organs during viral infections." (PMID 37946732, 2023). "Besides parasitic and bacterial models, in which MIF was shown to drive/mediate infection-related immune-pathological outcomes, analogous MIF-mediated effects were also documented to occur during experimental viral infections." (PMID 35464430, 2022).
viral infections (continued). "Furthermore, expression levels of pro−inflammatory cytokines such as IL−32, LTB, and MIF were markedly elevated in the severe group, with IL−32 persistently upregulated across all disease stages, reinforcing its known pro−inflammatory role in viral infections and lung pathology." (PMID 41200182, 2025). "Furthermore, we investigated the correlation between viral infection status (EBER1 and HPV16/18), MIF, and macrophage markers (CD68, CD11c, and CD163) in NPC cases using Spearman’s correlation test." (PMID 34407796, 2021). "A significant positive correlation between EBER1 levels and MIF expression levels in tumor nests and a significant positive correlation between HPV16/18 level and the score for CD11c(+) cells suggested the influence of viral infection on macrophage behavior." (PMID 34407796, 2021). "Furthermore, the lack report of MIF, SCF, HGF, MCP-1 and SCGF-β elevations in lethal virus infections may be due to the lack of laboratory examinations." (PMID 26028236, 2015).
endotoxemia (15 papers, 2009 to 2021). "Furthermore, mice deficient in the MIF gene, or those in which the MIF protein has been neutralized, are protected from lethal endotoxemia and septic shock." (PMID 19413900, 2009). "Macrophage migration inhibitory factor (MIF) is a cytokine implicated in various inflammatory processes that is rapidly released from preformed intracellular pools in response to multiple cellular and systemic noxious stimuli, including ischemia/reperfusion, endotoxemia and surgery." (PMID 34300206, 2021). "Employing a mouse endotoxic shock model, recombinant MIF was found to greatly enhance lethality when coinjected with lipopolysaccharide (endotoxin), whereas an anti-MIF antibody conferred full protection against lethal endotoxemia." (PMID 25821355, 2015). "Migration inhibitory factor is secreted by pituitary cells following LPS stimulation in vivo and this contributes significantly to circulating MIF in the post-acute phase of LPS-induced endotoxemia." (PMID 26617609, 2015). "Among these proteins was MIF, and the authors went on to show that blockade of MIF protected mice from LPS-induced lethality, indicating its prominent proinflammatory role in endotoxemia." (PMID 22496958, 2012). "Since the molecular cloning of MIF cDNA, MIF has been re-evaluated as a proinflammatory cytokine and pituitary-derived hormone that potentiates endotoxemia." (PMID 24281172, 2010). "Since the molecular cloning of MIF cDNA, MIF was reevaluated as a proinflammatory cytokine and pituitary-derived hormone that potentiates endotoxemia." (PMID 24281172, 2010). "MIF is an inflammatory cytokine that is rapidly released from preformed intracellular pools in response to diverse cellular and systemic stressors, including ischemia-reperfusion, endotoxemia and surgery." (PMID 32932965, 2020). "As both MIF and NLRP3 have been implicated in the pathogenesis of septic shock, we next investigated the effects of COR123625 on serum IL-1β and IL-18 in a mouse model of LPS-induced endotoxemia." (PMID 29884801, 2018). "Furthermore, co-injection of MIF with LPS increases lethality, while anti-MIF antibody protects mice against LPS-induced endotoxemia." (PMID 26617609, 2015). "Macrophage migration inhibitory factor (MIF) is a proinflammatory cytokine with molecular weight of 12 kDa and is released into the circulation by the anterior pituitary gland as a consequence of central nervous system (CNS) injury or as toxic response to endotoxemia." (PMID 32903462, 2020). "In conclusion, HS improved myocardial contractility and prevented circulatory failure induced by endotoxemia, which may attribute to improvement of intracellular calcium handling process and inhibitory effects on neutrophil infiltration and MIF production in hearts." (PMID 24371817, 2013). "In experimental endotoxemia, serum DDT levels are increased with a similar than MIF, and both proteins were detectable at similar concentration." (PMID 29924850, 2018). "The small molecule MIF antagonist, ISO-1 ((S,R)-3-(4-hydroxyphenyl)-4,5-dihydro-5-isoxazole acetic acid methyl ester), also protects mice against LPS-induced endotoxemia and reduces TNF-α production by peritoneal macrophages." (PMID 26617609, 2015). "Furthermore, MIF release could not be detected in a human endotoxemia model and is not produced by whole blood cells incubated with LPS." (PMID 20169062, 2010).
head and neck cancer (15 papers, 2013 to 2025). A primary or metastatic malignant neoplasm affecting the head and neck. "For instance, in head and neck cancer, elevated MIF levels were associated with increased expression of CD66b, a granulocyte/neutrophil marker, as well as lymph node metastasis, and poorer overall survival." (PMID 41159021, 2025). "We chose MIF and CD66b (neutrophil marker) because they have been shown to associate with advanced disease and poor survival in orohypopharynx carcinoma patients-another major subtype of head and neck cancer." (PMID 23409183, 2013). "Both MIF and neutrophils have been linked to enhanced tumoral migration and poor clinical outcome in patients with orohypopharynx carcinoma-another major subtype of head and neck cancer." (PMID 23409183, 2013). "This study investigated the relevance of AHNAK, MIF and tumor-infiltrating neutrophils (CD66b-positive cells) for the survival of patients with laryngeal carcinoma-a major subtype of head and neck cancer." (PMID 23409183, 2013). "Recently, our group identified direct interactions between head and neck cancer (HNC)-derived MIF and neutrophils both in vitro and in situ." (PMID 23409183, 2013). "Therapeutically, there is substantial data regarding MIF as a target in head and neck cancers." (PMID 41159021, 2025). "Induction of IFNβ post-IR followed by the interplay of IFN-induced proteins (STAT1, ISG15) and cytokines (IL-1β, IL-6, MIF) hints towards IR-induced inflammation contributing to initiation and progression of oral mucositis that affects a majority of head and neck cancer patients." (PMID 37384298, 2023). "Furthermore, macrophage migration inhibitory factor (MIF) promotes neutrophil chemotaxis that in turn leads to increased migratory capacity of tumor cells in an in vitro model of head and neck cancer." (PMID 33363012, 2020). "More importantly, we identified MIF as one of the 'missing links' in the tumor-neutrophil interraction and showed that head and neck cancer cells released MIF which, subsequently, enhanced the proinflammatory functions of neutrophils to promote tumoral migration." (PMID 23409183, 2013).
Parkinson disease (15 papers, 2012 to 2025). A progressive degenerative disorder of the central nervous system characterized by loss of dopamine producing neurons in the substantia nigra and the presence of Lewy bodies in the substantia nigra and locus coeruleus. "In Parkinson's disease, MIF suppresses inflammation and apoptosis while promoting autophagosome formation." (PMID 40881277, 2025). "The function of MIF in Parkinson's disease has been elucidated, but only a few studies have been conducted in PRE." (PMID 38801174, 2024). "In Parkinson’s disease (PD), MIF has been found to mediate a neuroprotective effect by suppressing inflammatory responses, inhibiting apoptosis, and inducing autophagy." (PMID 38178143, 2024). "One study showed that MIF overexpression elevated LC3-II levels in a Parkinson’s disease animal model, suggesting a neuroprotective effect." (PMID 39727941, 2024). "In agreement with its pleiotropic biological functions, emerging evidence indicates that MIF may play a complex role in neurodegenerative disorders with potential beneficial effects in Parkinson′s Diseases (PD) and amyotrophic lateral sclerosis (ALS)." (PMID 31936865, 2020). "MIF has been found to be expressed in the neocortex, hippocampus, hypothalamus, cerebellum, choroid plexus, and spinal cord in the CNS and up-regulated in AD and Parkinson disease." (PMID 32903462, 2020). "In an in vitro model of Parkinson’s disease (PD), overexpression of MIF could protect dopaminergic neurons and reduce neuronal neuroinflammation, while knockout of MIF in an AD mouse model could impair cognition, suggesting that MIF may be involved in the process of PD and even PD-CI." (PMID 36824264, 2023). "Given the wide spectrum of serum and CSF responses to pathological processes including neuroinflammation and neurodegenerative diseases such as AD and Parkinson's disease (PD), we have selected a 41 cytokine/chemokine panel and MIF to explore the CSF responses to high air pollution residency." (PMID 24133408, 2013). "MIF (macrophage migration inhibitory factor) reduces the expression of NLRP3 inflammasome and inflammatory factors induced by MPP+ (1-methyl-4-phenylpyridinium) in microglia, reducing DA neuronal damage and exerting protective effects against neuroinflammation induced by Parkinson’s disease." (PMID 36009120, 2022). "However, this MIF treatment did not affect the outcome on graft function and survival leaving the potential of MIF as a neuroimmune modulator in Parkinson's disease open." (PMID 22973314, 2012). "It has been shown that MIF may be involved in several disorders, including neurodegenerative disorders such as amyotrophic lateral sclerosis (ALS), Parkinson disease (PD), and Huntington disease (HD), that represent an unmet medical need." (PMID 32344747, 2020).
cardiac hypertrophy (14 papers, 2016 to 2025). "Similar findings were reported in mice subjected to abdominal aorta constriction-induced cardiac hypertrophy, where MIF deficiency worsened cardiac hypertrophy and decreased autophagy." (PMID 40092999, 2025). "Another study found that MIF deficiency exacerbated abdominal aorta constriction‐induced cardiac hypertrophy via mitigating autophagy." (PMID 38924383, 2024). "MIF-knockout mice showed heart contractile dysfunction, and MIF deficiency overtly exacerbated abdominal aorta constriction-induced cardiac hypertrophy and contractile anomalies." (PMID 31964409, 2020). "However, while clinical data implicated MIF as detrimental in HF caused by ischemia and inflammation, other studies suggested a protective function for MIF in cardiac remodeling in myocardial hypertrophy and fibrosis induced by pressure overload." (PMID 40092999, 2025). "Along these lines, in mice subjected to transverse aortic coarctation for 10 days, MIF-deficient mice showed significantly increased heart growth and cardiac fibrosis, suggesting that MIF reduced myocardial hypertrophy and fibrosis in pressure overload-induced cardiac hypertrophy." (PMID 40092999, 2025). "More recently, MIF was reported to confer protection against pressure overload-induced cardiac hypertrophy and fibrosis by regulating the miR-29b-3p/HBP1 axis and the Smad3-miR-29b/miR-29c axis, respectively." (PMID 40092999, 2025). "In this study, we adopted the gain‐of‐function strategy to overexpress MIF in TAC‐treated cardiac hypertrophy mice model." (PMID 38924383, 2024). "Taken together, these findings suggested that overexpression of MIF ameliorated cardiac hypertrophy and its consequences in TAC‐ treated mice." (PMID 38924383, 2024). "Overexpression of MIF reduced the cardiac hypertrophy in TAC‐treated mice and reduced Ang II‐induced oxidative stress in cardiomyocytes." (PMID 38924383, 2024). "In the current study, we found that MIF played a protective role in pressure overload‐induced cardiac hypertrophy." (PMID 38924383, 2024). "Here, we aimed to illustrate the mechanism of MIF in protecting against pressure overload‐induced cardiac hypertrophy." (PMID 38924383, 2024). "How MIF regulates the signaling pathways involved in cardiac hypertrophy progression and the regulatory network downstream MIF are not completely understood." (PMID 38924383, 2024). "In this study, we demonstrated that overexpression of MIF protected against pressure overload‐induced cardiac hypertrophy in a TAC treated mouse model." (PMID 38924383, 2024). "In transverse aortic constriction (TAC)‐induced mouse myocardial hypertrophy, MIF expression was enhanced and MIF antagonized myocardial hypertrophy and fibrosis via maintaining a redox homeostatic phenotype." (PMID 38924383, 2024). "Consistently, deletion of MIF exacerbated pressure overload‐induced cardiac hypertrophy via activating mTOR signaling and mitigating autophagy." (PMID 38924383, 2024). "Under pressure-overload conditions, MIF–/– mice showed more severe myocardial hypertrophy, systolic dysfunction, and myocardial fibrosis than WT mice." (PMID 36712241, 2022). "One study showed that macrophage migration inhibitory factor significantly reduced pressure overload-induced cardiac hypertrophy by activating mitophagy and autophagy." (PMID 34631840, 2021). "Additionally, the genetic deletion of MIF has been shown to aggravate cardiac hypertrophy in a moderate pressure overload animal model." (PMID 39727941, 2024). "Taken together, MIF could attenuate pressure overload‐induced cardiac hypertrophy through regulating the miR‐29b‐3p/HBP1 axis." (PMID 38924383, 2024). "Accumulating evidence has shown that MIF regulates cardiac hypertrophy." (PMID 38924383, 2024). "In conclusion, our findings suggest that MIF could attenuate pressure overload‐induced cardiac hypertrophy through regulating the miR‐29b‐3p/HBP1 axis." (PMID 38924383, 2024).
cardiac hypertrophy (continued). "Previous studies have indicated that macrophage migration inhibitory factor (MIF) might play a protective role in cardiac hypertrophy." (PMID 38924383, 2024). "In pressure overload induced cardiac hypertrophy, MIF protects against cardiac hypertrophy and fibrosis in response to hemodynamic stress via maintaining a redox homeostatic phenotype and attenuating stress‐induced activation of hypertrophic signaling pathways." (PMID 38924383, 2024). "Moreover, the inherent oxidoreductase activity of MIF also reduces the degree of myocardial hypertrophy under pressure-overload by limiting the oxidative stress of cardiomyocytes." (PMID 36712241, 2022). "Noticeably, the other series of studies also evaluated that MIF could protect cardiac cells against overload pressure-induced cardiac hypertrophy via activating Parkin-mediated macroautophagy or mitophagy." (PMID 34306312, 2021). "Therefore, combined with the published findings, MIF may play a protective role in the treatment of cardiac hypertrophy." (PMID 38924383, 2024). "Therefore, MIF could be utilized as a promising therapeutic target to treat the patients with cardiac hypertrophy." (PMID 38924383, 2024). "Although it is beyond the scope of our study to examine the precise mechanism responsible for cardiac hypertrophy in aged MIF−/− mice, deletion of the pro-inflammatory cytokine MIF in the heart may have break the balance between pro- and anti-hypertrophic cytokines in the heart with advanced aging." (PMID 26940544, 2016). "In conclusion, our findings suggest that overexpression of MIF regulates the miR‐29b‐3p/HBP1 axis and protects against pressure overload induced cardiac hypertrophy." (PMID 38924383, 2024). "CD74_MIF, CD74_APP and CD74_COPA pairs were significantly enriched by B cells and macrophages at different stages of cardiac hypertrophy, indicating that CD74 played a crucial role in inflammation activity in cardiac hypertrophy." (PMID 36805782, 2023). "This may be attributed to the fact that MIF can activate autophagy through AMPK-mTOR signaling, thereby alleviating the degree of cardiac hypertrophy in mice under stress loading conditions." (PMID 36712241, 2022).